RUNX1 (RUNX family transcription factor 1)
Diseases named in the same sentence as RUNX1 in open-access papers (continued):
Sharing a sentence is not in itself a finding about the gene and the disease.
acute myeloid leukemia (continued). "Previous studies show that germline and somatic mutations of RUNX1 are observed in many hematological malignancies such as myelodysplastic syndrome (MDS), acute lymphoblastic leukemia (ALL), acute myeloid leukemia (AML), and chronic myelomonocytic leukemia (CMML)." (PMID 36090034, 2022). "RUNX1 mutations are frequently detected in various myeloid neoplasms and implicate unfavourable clinical outcomes in patients with myelodysplastic syndrome (MDS) and acute myeloid leukaemia (AML)." (PMID 36467848, 2022). "RUNX1 and CSF3R are frequently co-mutated in the progression to acute myeloid leukemia from SCN." (PMID 35200567, 2022). "Previous reports have suggested that RUNX1 could be a potential therapeutic target of cancers, such as acute myeloid leukaemia, since this protein is an important regulator of haematopoiesis in vertebrates." (PMID 35740337, 2022). "Analysis also revealed an association with a pathway category deposited as “Acute Myeloid Leukemia”, which refers to ERK, PI3K and JAK-STAT signaling and transcription regulation pathways including mutated RUNX1 and the fusion genes AML1-ETO, PML-RARA and PLZF-RARA." (PMID 34502231, 2021). "The fusion gene RUNX1/RUNX1T1 is oncogenic in acute myeloid leukemia." (PMID 33483506, 2021). "RUNX1/RUNX1T1 is the most common fusion gene found in acute myeloid leukemia." (PMID 33217477, 2021). "However, current studies have found that RUNX1-ETO can also cause abnormal cell differentiation, but the fusion protein itself is insufficient to develop into acute myeloid leukemia (AML) unless there are additional mutations." (PMID 34434964, 2021). "Acute myeloid leukemia with the NUP98/RARG fusion gene and the RUNX1 mutation may be a special subtype of AML and may benefit from the alkaloid-based regimen." (PMID 33019444, 2020). "These cases were particularly intriguing because of the high rate of myelodysplastic syndrome (MDS) and acute myeloid leukemia (AML) in affected individuals, and demonstrated a key link between RUNX1 haploinsufficiency and predisposition to malignant hematopoiesis." (PMID 31313878, 2019). "Several acute myeloid leukemia (AML) predisposition syndromes are caused by innate mutations in transcription factors that affect embryonic hematopoiesis, such as Gata2 and Runx1, suggesting that perturbations in embryonic hematopoiesis affect the adult HSC compartment." (PMID 30374440, 2018). "The clinical impact of RUNX1 expression in cytogenetically normal acute myeloid leukemia (CN-AML) remained unknown, however." (PMID 26910834, 2016). "RUNX1/AML1/CBFA2/PEBP2αB was discovered as a common chromosomal translocation target in chronic myelogenous and acute myeloid leukemias, and its critical necessity for adult blood-cell production was discovered in RUNX1-null mice, which lacked definitive hematopoiesis." (PMID 21197465, 2011). "Furthermore, human PRDM3/EVI1 gene is frequently involved in chromosomal translocation with variety of partner genes, including AML1/RUNX1, leading to myelodysplasia and acute myeloid leukemia." (PMID 18231586, 2008). "One patient has developed acute myeloid leukemia (AML), and another was diagnosed with RUNX1-FPDMM due to thrombocytopenia onset following T-lymphoblastic lymphoma." (PMID 41458504, 2025). "Acute myeloid leukemia (AML) with RUNX1::RUNX1T1 fusion is well known to often demonstrate aberrant upregulation of CD19 expression." (PMID 40282530, 2025). "Additionally, conditions such as acute myeloid leukemia (AML) with RUNX1::RUNX1T1 fusion, AML with CBFB::MYH11 fusion, myeloid/lymphoid neoplasms with eosinophilia and specific gene rearrangements, and the blast phase of chronic myeloid leukemia (CML) must be excluded from the diagnosis." (PMID 41366999, 2025). "Core binding factor acute myeloid leukemia (CBF-AML) includes AML cases harboring RUNX1::RUNX1T1 or CBFβ::MYH11 fusion genes, which are classified as a favorable-risk group." (PMID 38802593, 2024).
acute myeloid leukemia (continued). "Runt-related transcription factor 1 (RUNX1)::RUNX1 partner transcriptional co-repressor 1 (RUNX1T1) acute myeloid leukemia (AML) is a subtype of acute leukemia primarily classified as French American British M2." (PMID 38633925, 2024). "The Runt-related transcription factor (RUNX) family, historically known as the polyoma enhancer-binding protein 2 α (PEBP2α), acute myeloid leukemia (AML) and core binding factor α (CBFα) family of proteins, comprises three members: RUNX1, RUNX2 and RUNX3." (PMID 36831308, 2023). "There are three RUNX genes (RUNX1, RUNX2, and RUNX3) in humans that encode acute myeloid leukemia (AML), the alpha subunit of polyomavirus enhancer-binding protein 2 (PEBP2α), or core-binding factor subunit α (CBFα)." (PMID 36231060, 2022). "For instance, in humans, RUNX1 is a well-described target of chromosomal translocations leading to acute myeloid leukemia (AML)." (PMID 37073169, 2022). "Somatic runt-related transcription factor 1 (RUNX1) mutations are the most common mutations in various hematological malignancies, such as myelodysplastic syndrome (MDS) and acute myeloid leukemia (AML)." (PMID 35765406, 2022). "For example, in acute myeloid leukemia (AML), an association between SNHG7 and SNHG12 lncRNAs and specific clinical/molecular features, including white blood cell (WBC) counts and mutations in IDH1, RUNX1, and NPM1 genes, shows high value of SNHG7 in correlation with extensive features." (PMID 35111760, 2021). "Binding of AML/Runx1 (Acute myeloid leukemia 1/Runt-related transcription factor 1) to FOXP3 leads to upregulation of Treg-related molecules by repressing IL-2 and IFN-γ levels." (PMID 34675933, 2021). "This would suggest that RUNX1 may limit angiogenesis in some circumstances, and in support, silencing of RUNX1 in acute myeloid leukaemia cells increased VEGFA promoter activity and conditioned media from these cells led to a significant improvement in the in vitro angiogenic capacity of HUVECs." (PMID 32154891, 2020). "RUNXOR regulates the expression of RUNX1 in acute myeloid leukemia (AML) cells by binding to its promoter and enhancer." (PMID 33353065, 2020). "A rare inherited blood disorder caused by mutations of the RUNX1 gene, clinically characterized by low platelet count, abnormal platelet function, and an increased risk of developing other blood disorders or cancers such as myelodysplastic syndrome (MDS) and acute myeloid leukemia (AML)." (PMID 31313878, 2019). "We have previously reported that RUNX1 is strongly required for the maintenance and progression of acute myeloid leukemia (AML) and RUNX cluster inhibition would be a novel strategy to control AML21–24." (PMID 29686309, 2018). "RUNX1 (Run-Related Transcription Factor 1) also known as AML1 (acute myeloid leukemia 1 gene) is a tumor suppressor gene with a length of 1,196,949 bp and was original identified in acute myeloid leukemia (AML)." (PMID 26920143, 2016). "Translocations involving RUNX1 are known to decrease the function of the encoded protein in myelodysplastic syndromes (MDS) and acute myeloid leukemia (AML)." (PMID 26671595, 2015). "Haploinsufficiency of RUNX1, due to heterozygous loss-of-function mutations, is associated with familial platelet disorder and predisposition to acute myeloid leukemia (FPD-AML)." (PMID 23717578, 2013). "RUNX1 is the most frequent target for chromosomal translocation in human acute myeloid leukemia (AML), generating the oncogenic fusion proteins such as RUNX1/ETO." (PMID 24078903, 2013). "The transcription factor RUNX1 is one of the most frequent genes involved in chromosomal translocations found in acute myeloid leukemia (AML)." (PMID 24348510, 2013).
acute myeloid leukemia (continued). "In agreement with previous studies, USP10 acts as an oncoprotein in hepatocellular carcinoma, esophageal squamous cell carcinoma, glioblastoma, and acute myeloid leukemia through the stabilization of YAP, ANLN, RUNX1, and FLT3." (PMID 40605431, 2025). "RUNX1, also known as AML1, is best known for its critical function in definitive hematopoiesis and lymphocyte development, and its frequent mutations are strongly implicated in leukemogenesis, particularly in acute myeloid leukemia (AML)." (PMID 40990016, 2025). "In contrast, a truncated RUNX1::RUNX1T1 isoform, generated via alternative splicing at exon 9, can elicit acute myeloid leukemia transformation in murine HSPCs." (PMID 38201282, 2023). "Loss-of-function mutations in MGA have been commonly identified in several hematological neoplasms, including acute myeloid leukemia (AML) with RUNX1::RUNX1T1, however, very little is known about the impact of these MGA alterations on normal hematopoiesis or disease progression." (PMID 37790524, 2023). "In acute myeloid leukemia (AML), the so-called master transcription factors such as RUNX1, KMT2A, and HOX are frequently disrupted by chromosomal translocations, resulting in neomorphic oncogenic fusion genes." (PMID 38201282, 2023). "Recurrent gene rearrangements are present in 30–40% of acute myeloid leukemia (AML), and well-described driver fusions sometimes suffice to diagnose leukemias (for example, PML::RARA, or RUNX1::RUNX1T1 among others)." (PMID 37699001, 2023). "Somatic mutations and chromosomal rearrangements involving Runx1 are frequently observed in abnormal hematopoietic cells in myelodysplastic syndrome (MDS), acute myeloid leukemia (AML), acute lymphoblastic leukemia (ALL), and chronic myelomonocytic leukemia (CMML) patients." (PMID 35551452, 2022). "Somatic RUNX1 aberrations are recurrently detected in various myeloid malignancies, such as myelodysplastic syndrome (MDS), acute myeloid leukemia (AML), and myeloproliferative neoplasms." (PMID 35884491, 2022). "Increasing knowledge about the impact of runt-related transcription factor 1 (RUNX1) gene mutation on characteristics and outcome of patients with de novo acute myeloid leukemia (AML) has led to its establishment as a provisional entity in the 2016 WHO classification." (PMID 34059800, 2021). "These include the RUNX1-ETO fusion, which is the most common cytogenetic abnormality in acute myeloid leukemia, and the ETV6-RUNX1 fusion, which occurs in ∼25% of cases of childhood precursor B cell acute lymphoblastic leukemia." (PMID 34810221, 2021). "Cooperation of RUNX1 and JAK-STAT alterations has already been suggested to play a role in acute myeloid leukemia (AML) development." (PMID 34299194, 2021). "RUNX1 and RUNX2 expression in breast cancer was relatively high, ranking second after acute myeloid leukemia (LAML) for all the analyzed tumor types, indicating their potential role in breast cancer." (PMID 34485309, 2021). "RUNX1 is a transcription factor important for hematopoietic cell development during embryogenesis and as a hybrid protein formed by fusions of AML1 and ETO, a genetic aberration leading to the acute myeloid leukemia subtype M2." (PMID 32240523, 2020). "ETV6, RUNX1, and GATA3, described also in acute myeloid leukemia, are deleted or inactivated in ETP-ALL, and correlate with poor outcome: ETV6 (12p13) mutations account for ~25% of ETP-ALL, whilst RUNX1 (21q22), and GATA3 (10p14) mutations are less common." (PMID 32185137, 2020). "In acute myeloid leukemia, CBFA2T3 can be a translocation partner of RUNX1, producing a chimeric protein with breakpoints usually between exons 1 and 2, or exons 3 and 4 of CBFA2T353." (PMID 30926794, 2019).
acute myeloid leukemia (continued). "Three miRNA target genes also include NRAS, RUNX1, MAPK1, which are precisely enriched in acute myeloid leukemia pathway." (PMID 28473658, 2017). "RUNX1 transcription factor (TF) is a key regulator of megakaryocytic development and when mutated is associated with familial platelet disorder and predisposition to acute myeloid leukemia (FPD-AML)." (PMID 23717578, 2013). "RUNX1 (also known as AML1) has been extensively documented as an important factor in hematopoiesis and in the etiology of acute myelogenous leukemia." (PMID 21203558, 2010). "For example, acute myeloid leukemia (AML) 1-ETO, an AML-specific fusion-protein, has been reported to bind to human rRNA genes and promote Pol I transcription in malignant myeloid cells, while AML1 (Runx1) downregulates Pol I transcription." (PMID 34069807, 2021). "In acute myeloid leukemia, CBFA2T2 has been identified as a fusion partner of RUNX1." (PMID 29162985, 2017). "RUNX1 is frequently translocated in myeloid and lymphoid malignancies, with fusion of RUNX1 to the Ets family TEL TF in B-cell acute lymphoblastic leukaemia and to ETO in acute myeloid leukaemia." (PMID 26883634, 2016). "Furthermore, we observed that inhibition of RUNX1/ETO in Kasumi1 cells and in RUNX1/ETO positive primary acute myeloid leukemia patient samples leads to up-regulation of miR144/451." (PMID 26990877, 2016). "The core binding factor (CBF) protein complex, composed of RUNX1 and CBFB, is important for myeloid differentiation and recurrently altered in acute myeloid leukemia (AML) through genomic rearrangements." (PMID 31896782, 2020). "In addition, chromosomal translocations between the EWSR1 and FLI1 loci and between the AML1 (also known as RUNX1) and ETO (also known as RUNX1T1) loci, which are involved in Ewing’s sarcoma and acute myeloid leukemia (AML), respectively, have been generated by CRISPR in human cell lines." (PMID 26060510, 2015). "One of the most frequent genetic aberrations in acute myeloid leukemia (AML) is chromosomal translocation between AML1/RUNX1 on chromosome 21 and ETO gene on chromosome 8 resulting in the expression of chimeric oncogene AML1-ETO." (PMID 25861270, 2015). "The fusion oncogene RUNX1/RUNX1T1 could reprogram a large transcriptional network to establish and maintain acute myeloid leukemia (AML) via intricate PPI interactions and kinase-driven phosphorylation events in both adult and pediatric patients." (PMID 39822248, 2024). "Moreover, in one of our earlier studies the RUNX1 and RUNX3 expression level assessment was performed on a group of patients diagnosed with acute myeloid leukemia (AML)." (PMID 36005134, 2022). "Genetic alterations of these genes (CBFB, RUNX1, RUNX2, and RUNX3) can alter normal binding to DNA by CBF, thus resulting in a failure of hematopoiesis or hematologic malignancies, particularly acute myeloid leukemia (AML)." (PMID 36011278, 2022). "The distribution of RUNX1-RUNXT1, PML-RARA, CBFB-MYH11, BCR-ABL1p210, and KMT2A-MLLT3 in the pediatric population with acute myeloid leukemia (AML) in many countries of Latin America is largely unknown." (PMID 36452349, 2022). "The results showed that RUNX1 expression was higher in CESC, COAD, ESCA, GBM, KIRC, acute myeloid leukemia (AML), pancreatic adenocarcinoma (PAAD), READ, STAD, thymoma (THYM), UCEC, and uterine carcinosarcoma (UCS) than in adjacent normal tissue samples (all P < 0.05)." (PMID 35534796, 2022). "The fusion genes CBFB/MYH11 and RUNX1/RUNX1T1 block differentiation through disruption of the core binding factor (CBF) complex and are found in 10–15% of adult de novo acute myeloid leukemia (AML) cases." (PMID 31896782, 2020). "Both RUNX1 and CBFB undergo chromosomal rearrangements in acute myeloid leukemia (AML)." (PMID 25612891, 2015). "Furthermore, oncogenic rearrangements of RUNX1 and/or CBFB are common in acute myeloid leukemia (AML)." (PMID 26561834, 2015).
acute myeloid leukemia (continued). "Interestingly, it was reported that METTL3 mRNA and protein expression was increased in acute myeloid leukemia (AML) cells compared to healthy hematopoietic stem and progenitor cells, and a higher expression was reported in pediatric ALL ETV6/RUNX1-positive patients when compared to controls." (PMID 36428851, 2022). "CBFA2T3 (MTG16), CBFA2/RUNX1 Partner Transcriptional Co-Repressor 3, has not been clearly studied in lung cancer although the CBFA2T3-GLIS2 fusion transcript is well proven as a novel common feature in pediatric cytogenetically normal acute myeloid leukemia (AML)." (PMID 34540825, 2021). "This last designation is in contrast to the WHO, which still requires blast counts of at least 20% for a diagnosis of acute myeloid leukemia (AML) in the absence of certain specific AML-defining genetic abnormalities (e.g., PML::RARA fusion, RUNX1::RUNX1T1 fusion, etc)." (PMID 39941875, 2025). "Furthermore, while multiple detailed studies have interrogated the relationship between native RUNX1 and the RUNX1-ETO fusion protein in acute myeloid leukemia (AML), such analyses are lacking in B-ALL16,17." (PMID 36411286, 2022). "Interestingly, fusion RUNX1/CBFA2T2 transcript is highly upregulated compared with wild-type CBFA2T2 gene, suggesting that CBFA2T2 alone might not be sufficient for the development of acute myeloid leukemia." (PMID 29162985, 2017).